NLRC4 (NLR family CARD domain containing 4)
Diseases named in the same sentence as NLRC4 in open-access papers (continued):
Sharing a sentence is not in itself a finding about the gene and the disease.
bacterial infection (continued). "It will be interesting to know if these bacterial infections, or even sub-clinical bacterial infections, are sufficient to drive NLRC4-inflammasome activation via direct renal infection or circulating bacterial products like flagellin." (PMID 27706238, 2016). "Although the precise effector mechanisms of IL-1β and IL-18 remain to be elucidated, these cytokines have been reported to be important mediators induced by NAIP/NLRC4 to host resistance to bacterial infections." (PMID 25071770, 2014). "Under certain conditions like bacterial infection of macrophages, another inflammasome, the NLRC4/Ipaf inflammasome, has been reported to downregulate autophagy independent of IL-1β production." (PMID 24456929, 2013). "Thus, NAIP is a critical inhibitor of programmed cell death in host cells, and NAIP assembles with NLRC4 to form a fully functional inflammasome, which can lead to secretion of cytokines, induction of cell death, inflammation, and bacterial infection control." (PMID 37006312, 2023). "In this context, flagellin is known to trigger NLRC4 inflammasome activation, since either deletion or mutation of flagellin FliC from Salmonella typhimurium or Legionella pneumophila abolished NLRC4 inflammasome activation in mouse macrophages upon bacterial infection." (PMID 37026001, 2023). "Importantly, recent studies have demonstrated a role for NAIP/NLRC4 inflammasomes in response to non-bacterial infections and sterile inflammation triggers." (PMID 36481780, 2022). "However, recent studies have demonstrated that NAIP/NLRC4 is also activated in non-bacterial infections, and in sterile inflammation." (PMID 36481780, 2022). "However, inflammasomes including AIM2, NLRP3 and NLRC4 are also expressed in neutrophils and involved in IL-1β secretion during bacterial infection." (PMID 34017331, 2021). "NLRP3 activation may therefore act as a “safety net” to preserve inflammasome activation during bacterial infection in the face of suboptimal NAIP/NLRC4 activation." (PMID 33380493, 2021). "Moreover, research involving NLRC4 immune regulation has mainly focused on using gene knockout models in mice to investigate the role of NLRC4 in activating CASP1 in various bacterial infections." (PMID 34276697, 2021). "This bacterial OMV-driven NLRC4 inflammasome signaling may provide an efficient host defense mechanism as a rapid sensing machinery against bacterial infection." (PMID 33312172, 2020). "The identification of the critical substrates involved in the restriction of bacterial infection via the NAIP/NLRC4 inflammasomes provides important information for our understanding of the biology of these important platforms that operate for host protection against pathogenic bacteria." (PMID 31251782, 2019). "Together, these data indicate a cross talk between lysosomes and NAIP/NLRC4 inflammasomes that impact the control of bacterial infections and opens new avenues for the development of inflammasome-based therapeutic strategies for non-infectious pathologies such as tumors." (PMID 25071770, 2014). "It was recently shown that there is cooperation between NLRP3 and NLRC4 inflammasomes in vivo during S. typhimurium infection, and that deficiency of either NLRP3 or NLRC4 does not change the bacterial infection in the mice." (PMID 22768222, 2012). "However, recent reports have indicated the involvement of NLRC4 in non-bacterial infections and sterile inflammation, even though the role of NAIP proteins and the exact molecular mechanisms underlying inflammasome activation in these contexts remain to be elucidated." (PMID 38124741, 2023). "NLRC4 responds to bacterial flagellin and a conserved type III secretion system (TTSS) rod component, recruits pro-caspase-1 to directly form NLRC4 inflammasome and involves in a variety of pathogenic bacterial infection, such as Salmonella, Shigella, Pseudomonas aeruginosa." (PMID 34513725, 2021).
bacterial infection (continued). "The activation of the NAIP/NLRC4 pathway by bacterial protein ligands, in particular flagellin, and the relative contribution of the different ligands to inflammasome activation during bacterial infection are better characterized in murine macrophages than in human cells." (PMID 33380493, 2021). "NAIP/NLRC4-mediated responses are related to the restriction of bacterial growth due to the active caspase-1-mediated canonical and non-canonical effector mechanisms, highlighting the importance of this inflammasome as a host defense mechanism against a large number of bacterial infections." (PMID 25071770, 2014). "In this article, we shortlisted activated target genes in monocytes during acute bacterial infection, including VNN1, NLRC4, CYP1B1, PFKFB3, LILRA5, NFKBIA or NFKBIZ." (PMID 40581066, 2025). "Our study uses flagellin-deficient L. pneumophila to highlight that TNF also licenses rapid activation of multiple inflammasomes to restrict bacterial infection independently of flagellin and NAIP5/NLRC4 inflammasome activation." (PMID 37279255, 2023). "Since bacterial infections typically activate numerous innate immune pathways, including TLRs, it has been difficult to separate the effects of NAIP/NLRC4 activation from the downstream pro-inflammatory effects of TLR activation." (PMID 29263322, 2017). "Next, to examine whether VopQ-induced autophagy suppresses the NLRC4 inflammasome, we performed the short hairpin RNA (shRNA) knockdown of ATG5, one of the components of autophagy in NLRP3-deficient BMMs and assessed inflammasome activation upon bacterial infection." (PMID 23357873, 2013). "The participation of NAIP in non-bacterial infection was also demonstrated in HIV-1-infected human monocyte-derived macrophages, in which hNAIP was activated by HIV-1 glycoprotein 41 (gp41) leading to the NLRC4 recruitment and IL-18 secretion." (PMID 38124741, 2023). "Studies of NAIP/NLRC4 inflammasome focus mainly on conditions of bacterial infection, due to the fact that quite a few gram‐negative bacteria can induce pyroptosis through NLRC4‐caspase‐1‐dependent pathway." (PMID 37817895, 2023). "Because neutrophils do not die by pyroptosis after NLRC4 inflammasome activation, it is believed that these cells can maximize the host’s pro-inflammatory response against bacterial infection." (PMID 37006312, 2023). "Our data emphasize the protective nature of NLRP10 against microbial pathogens, thus adding NLRP10 to the group of NLR family members such as NOD1, NOD2, NLRC4, NLRP3, and NLRP12 that initiate pro-inflammatory signaling to mediate host resistance toward bacterial infections." (PMID 29163529, 2017). "Therefore, in the process of bacterial infection, the leakage of a small amount of flagellin into the host cytoplasm through T3SS or T4SS may trigger NLRC4 activation." (PMID 34276697, 2021). "The full-length NLRC4 inflammasome is inert, but NLRC4 lacking the c terminal LRR is active, allowing caspase 1 and the pyroptosis pathway to be activated for efficient bacterial infection eradication." (PMID 38328423, 2024).
cancer (36 papers, 2014 to 2025). A tumor composed of atypical neoplastic, often pleomorphic cells that invade other tissues. "Epithelial human NLRC4 promotes patient survival and is associated to Type-I Interferon signaling and immune infiltration in cancer." (PMID 38652550, 2024). "NLRC4 expression in human cancer cells mediates a type I IFN reprogramming, and is associated with high microsatellite instability in patient tumors." (PMID 38652550, 2024). "In multiple human carcinomas (colorectal, lung, and skin), we confirmed that NLRC4 expression in patient tumors was strongly associated with type I IFN genes, immune infiltrates, and high microsatellite instability." (PMID 38652550, 2024). "Many NLR proteins have been linked to cancer development via inflammasome-dependent pathways, including NLRC4 and NLRP1." (PMID 34854889, 2021). "Aberrant activation of NLRC4 has been implicated in other inflammatory disorders and cancer." (PMID 41062723, 2025). "Similar to AIM2 and NLRP3, NLRC4 is implicated in various types of cancer." (PMID 40692785, 2025). "Obesity, often associated with a poor prognosis in breast cancer, has been linked to NLRC4 inflammasomes, which may accelerate cancer development and progression." (PMID 40671967, 2025). "Our combined analysis using genetic editing, RNA-seq, and proteomics enabled us to identify the pathway by which NLRC4 expression associates with enhanced DC profiles and T cell responses in cancer patients, controlling the evolution of the disease and improving the survival of patients." (PMID 38652550, 2024). "Small molecules that enhance or disrupt the interaction between NLRC4 and its interacting proteins represent a promising strategy to target NLRC4-mediated pathways in contexts such as cancers, infectious diseases, and autoinflammatory disorders." (PMID 41062723, 2025). "NLRC4 expression in human cancer cells mediates the release of type I IFN chemokines and myeloid growth factors to directly induce maturation of DCs in vitro." (PMID 38652550, 2024). "Here we describe what we believe is a novel role for epithelial NLRC4 in cancer progression and invasiveness." (PMID 38652550, 2024). "The results showed that the mRNA expression levels of CHMP2A in cancer tissues were lower than those in normal tissues, and the expression of NLRC4 was just the opposite." (PMID 37077542, 2023). "The Gasdermin (GSDM) family member genes NLRP3, NLRC4, NLRP1, AIM2, IL-1β, and IL-18 are linked to TIME, and the immunosuppressive microenvironment can be overcome by targeted pyroptosis therapy in cancers." (PMID 36882663, 2023). "Among the PRGs, CHMP2A and NLRC4 showed the most significant difference in expression between cancer and adjacent cancerous normal tissues." (PMID 37077542, 2023). "CHMP2A and NLRC4 were found to be variables in the prognostic model, and the difference of their expression in cancer and adjacent cancerous normal tissues has been verified in separate cohorts from our hospital." (PMID 37077542, 2023). "Cleaved IL-1, caspase 1, and LDH levels increased in HEK293T and H1299 cells when NLRC4 was overexpressed, implying the death of more cancer cells." (PMID 36437954, 2022). "In this review, we highlight the role of the NAIP/NLRC4 inflammasome in host defense, autoinflammatory diseases, cancer, and cell death." (PMID 33494299, 2021). "The functional role of NLRC4 in cancer appears to be highly context dependent." (PMID 41062723, 2025). "Hence, NLRC4 expression can trigger a type I IFN immune reprogramming in human cancer cells that is observed in patient tumors from various cancer types and confers lower risk of metastatic progression." (PMID 38652550, 2024). "Thus, we shed light on the epithelial innate immune sensor NLRC4 as a therapeutic target to promote an efficient antitumor immune response against the aggressiveness of various carcinomas." (PMID 38652550, 2024). "Future studies will be needed to clarify the function of NLRC4 in cancer using littermate controls." (PMID 33494299, 2021).
cancer (continued). "Many of the studies related to NLRC4 in cancer have employed knockout mouse models." (PMID 34276697, 2021). "NLRC4 plays an important role in limiting cancer progression." (PMID 31492049, 2019). "Also consistent with our correlation of T cell infiltration in cancer patients with NLRC4 protein expression, an increase of gut intraepithelial lymphocytes was detected in the patient harboring the NLRC4 activating mutation V341A, leading to enterocolitis autoinflammatory syndrome." (PMID 38652550, 2024). "Since SINE RNAs robustly accumulate early during malignant cellular transformation and de novo purine synthesis contributes to the proliferation of cancer cells, we speculate that these DAMPs could be sensed intrinsically by epithelial cell–derived NLRC4, leading to a robust immune response." (PMID 38652550, 2024). "Additionally, NLRC4 could be a potential therapeutic approach for various cancer treatments." (PMID 40692785, 2025). "NLRP1, NLRP3, NLRC4, NLRP6, and AIM2 have been demonstrated to influence the pathogenesis of cancer by modulating innate and adaptive immune responses, cell death, and proliferation." (PMID 39684769, 2024). "The expression of selected 6 PRGs (GSDMC, GSDMD, GSDME, NLRP3, NLRC4, and IL1B) was assessed in 6 types of cancers and adjacent normal tissues." (PMID 36605187, 2022). "With regard to up-regulated DEGs enriched in immune response, it is now well-established that FGR, CXCL1, NLRC4 and S100A9 influence the pathogenesis of cancer by modulating immune responses and promoting progression, aggressiveness and cell survival 32-35." (PMID 32922167, 2020). "The NLR family (NLRP1, NLRP3, NLRC4, NLRP6, and NLRP12) and their binding partners have mixed roles in the pathogenesis of a variety of cancers." (PMID 33584697, 2020). "Of these, NLRP1, NLRP3, NLRC4, NLRP6, and AIM2 influence the pathogenesis of cancer using various mechanisms of action." (PMID 33614494, 2020). "NLRP1, NLRP3, NLRC4, NLRP6, NLRP7, and NLRP12 have mixed roles in the pathogenesis of a variety of cancers as reviewed here in details." (PMID 33584697, 2020). "Several inflammasomes including NLRP3, NLRP1, NLRC4, pyrin and AIM2 play a vital role in cancer pathogenesis through their regulation of immunity and apoptosis." (PMID 31492049, 2019). "The protective role of inflammasomes against tumors and cancer is not always linked to caspase‐1 and IL‐18; for example, research shows that NAIP1, a component of NLRC4, can prevent STAT3 activation and inhibit antiapoptotic gene expression." (PMID 40671967, 2025). "We compared the expression level of NLRC4 in pan-cancer and found that it was much lower in LUAD tissues than in normal tissues." (PMID 36437954, 2022). "A third group of cancers comprised of BLCA, BRCA, UCEC, LIHC, STAD, PRAD and THCA showed a similar expression pattern with first group of cancers except for the contrast behavior of NLRP3, NLRC4, PRF1, CASP1, CASP4, and GZMA (downregulated in this group)." (PMID 36605187, 2022). "We observed that NLRP7 (n = 8), AIM2 (n = 10), CASP8 (n = 6), GSDMA (n = 5), GSDMB (n = 8), and GSDMC (n = 12) mainly showed hypomethylation in most cancers, and PLCG1 (n = 11), NLRP6 (n = 13), ELANE (n = 11), CASP6 (n = 5), NLRC4 (n = 12), and PYCARD (n = 8) showed hypermethylation in most cancers." (PMID 35246158, 2022). "However, recent studies demonstrated that the regulation and suppression of NLRC4 is not always consistent between cancer models or even within the same CRC model." (PMID 33614494, 2020).
cancer (continued). "We further confirmed a strong positive correlation between NLRC4 expression with myeloid lineage markers from the TCGA data set, including specific macrophage marker CD163 and common myeloid markers CD68 and CD33, suggestive of a myeloid origin of NLRC4 in human cancer." (PMID 27708283, 2016). "Although there is little literature on the estrogen receptors (ERalpha, ERbeta, and GPR30) for cancer and in connection with NLRP3, their impact on NLRC4 and AIM2 is not described yet." (PMID 32645874, 2020). "Based on the literature, we conclude that the anti-cancer properties of lentinan are not mediated by inflammasomes since lentinan did not alter AIM2 mRNA expression nor activation of NLRP3 and NLRC4 inflammasomes." (PMID 28465544, 2017).
infectious disease (6 papers, 2017 to 2025). A disorder directly resulting from the presence and activity of a microbial, viral, or parasitic agent in humans. "Recently, the NLRC4 inflammasome was associated with host susceptibility in infectious diseases, mainly due to its ability to inhibit nitric oxide secretion within macrophages, leading to poor parasite control." (PMID 40431153, 2025). "NLRP1 and NLRC4 have classically been associated with inflammatory and infectious diseases." (PMID 40332346, 2025). "Therefore, although NLRC4 is associated with infectious diseases and MAS, high levels of IL-18 seem to be only associated with the latter, and patients with refractory severe MAS have better therapeutic effects after using IL-18 blockers and gamma interferon blockers (a cytokine induced by IL-18)." (PMID 34276697, 2021). "This discovery enhances our understanding of the role of the NAIP/NLRC4 inflammasome in infectious diseases." (PMID 40158217, 2025). "The role of NLRC4 in disease has been investigated in various models of infectious and non-infectious diseases." (PMID 28961278, 2017). "The NLR family pyrin domain-containing protein 1 (NALP/NLRP1) and protein 3 (NLRP3), as well as NLR family CARD domain-containing protein 4 (NLRC4) inflammasomes, are the best-known inflammasomes in immune and infectious diseases." (PMID 40332346, 2025).
neurodegenerative disease (5 papers, 2020 to 2025). A disorder of the central nervous system characterized by gradual and progressive loss of neural tissue and neurologic function. "NLRC4 is crucial in regulating inflammation in aging (Inflammaging) which contributes to the development of neurodegenerative diseases like PD." (PMID 33584697, 2020). "The focus of this study is on the NLRP1, NLRP3, and NLRC4 inflammasomes because they have garnered the most attention in the progression of neurodegenerative diseases." (PMID 31915018, 2020). "In addition to NLRP3, other inflammasomes such as AIM2, NLRC4 and NLRP1 and their downstream effector molecules have been found to play pathological roles in neurodegenerative diseases." (PMID 39710713, 2024). "Given clinical advancement of NLRP3 inhibitors in neurodegenerative disease, we questioned whether NLRP3 inhibition is sufficient to mitigate cytokine release and pyroptosis downstream of other inflammasomes such as NLRC4." (PMID 37575265, 2023).
immunodeficiency (4 papers, 2018 to 2022). Failure of the immune system to protect the body adequately from infection, due to the absence or insufficiency of some component process or substance. "The upregulation of NEAT1 has been shown to promote the release of several inflammasomes (NLRP3, NLRC4, and AIM2) and pro-inflammatory cytokines (CXCL10, IL-6, and IL-1β), resulting in an immune response in inflammatory and immune diseases." (PMID 35127819, 2021).
inflammation (4 papers, 2018 to 2023). Aberrant reaction of the microcirculation characterized by movement of fluid and leukocytes from the blood into extravascular tissues. "Intestinal levels of IL-1β correlate well with severity of intestinal inflammation and NLRC4 inflammasome deficiency still results in IL-1β production, suggesting other signaling rather than NLRC4 inflammasome plays dominant role in IL-1β production." (PMID 29456533, 2018). "For example, flagellin levels have been reported to be elevated in several murine models of intestinal inflammation, and flagellin can activate pro-inflammatory gene expression via TLR5 and the NLRC4 inflammasome." (PMID 34732258, 2021).
metabolic disorders (4 papers, 2023 to 2025). "In summary, studies should be carried out to illustrate the role and mechanism of other inflammasomes, including AIM2, NLRP1, NLRP6 and NLRC4 inflammasomes, in metabolic disorders." (PMID 40433411, 2025). "These additional putative mono/oligogenic SLE genes are involved in type I IFN regulation (DDX58, NLRC4 and PACSIN1), disruption of B cell and T cell tolerance (DOCK8, FAS and LRBA) and metabolic disorders (CYBB, MAN2B1, SLC7A7)." (PMID 40386946, 2025).